KAAG1 (kidney associated DCDC2 antisense RNA 1)
Synonyms: RU2AS; RU2
Gene: Long non-coding RNA gene on chromosome 6 (24,356,903 to 24,358,285, forward strand). Ensembl gene ENSG00000146049.
Genetic constraint (gnomAD): Loss-of-function variants: 0 observed, 0.31 expected, observed/expected ratio (o/e) 0, 90% interval 0 to 1.86. That is too few expected variants to judge how well the gene tolerates losing a copy. Missense variants: 124 observed, 129.16 expected, observed/expected ratio (o/e) 0.96, 90% interval 0.83 to 1.11. Synonymous variants: 45 observed, 55.75 expected, observed/expected ratio (o/e) 0.81, 90% interval 0.63 to 1.03.